ENTPD4 (ectonucleoside triphosphate diphosphohydrolase 4)
Description:
[Isoform 1]: Catalyzes the hydrolysis of nucleoside triphosphates and diphosphates in a calcium- or magnesium-dependent manner, with a preference for pyrimidines. Preferentially hydrolyzes UTP and TTP. AMP, ADP, ATP and UMP are not substrates. Preferentially activated by Ca(2+) over Mg(2+). [Isoform 2]: Has a broad substrate specificity with the ability of cleaving all nucleotide di- and triphosphates with the exception of adenosine di- and triphosphate (ADP and ATP). Preferentially hydrolyzes CTP, UDP, CDP, GTP and GDP. Can use either Ca(2+) or Mg(2+) equally.
Synonyms: UDPase; KIAA0392; LALP70; LYSAL1; LAP70; NTPDase-4
Tractability: Antibody: UniProt predicts a signal peptide or a membrane-spanning region. PROTAC: ubiquitination databases record sites on it.
Target class: Enzyme; Hydrolase
Gene: Protein-coding gene on chromosome 8 (23,385,783 to 23,457,716, reverse strand). Ensembl gene ENSG00000197217.
Subcellular location: Cytoplasmic vesicle, autophagosome membrane (Isoform 1); Lysosome membrane; Golgi apparatus membrane (Isoform 2)
Subcellular location (Human Protein Atlas): Vesicles
Pathways (Reactome):
Metabolism: Phosphate bond hydrolysis by NTPDase proteins
Gene Ontology:
Molecular function: CDP phosphatase activity; CTPase activity; GDP phosphatase activity; GTPase activity; nucleoside diphosphate phosphatase activity; protein binding; ribonucleoside triphosphate phosphatase activity; UDP phosphatase activity; hydrolase activity
Biological process: CTP metabolic process; GDP catabolic process; nucleobase-containing small molecule catabolic process; UDP catabolic process; purine ribonucleotide metabolic process; pyrimidine ribonucleotide catabolic process
Cellular component: autophagosome membrane; Golgi membrane; lysosomal membrane; Golgi apparatus; membrane
Genetic constraint (gnomAD): Loss-of-function variants: 52 observed, 72.36 expected, observed/expected ratio (o/e) 0.72, 90% interval 0.57 to 0.9. The upper end of that interval is the gene's LOEUF score, 0.9, which puts it in group 3 of 6, group 1 being the genes least tolerant of losing a copy. Missense variants: 737 observed, 764.37 expected, observed/expected ratio (o/e) 0.96, 90% interval 0.91 to 1.02. Synonymous variants: 263 observed, 291.29 expected, observed/expected ratio (o/e) 0.9, 90% interval 0.82 to 1.
Homologues: Orthologues: chimpanzee ENTPD4 (99% identical), macaque ENTPD4 (98% identical), rabbit ENTPD4 (96% identical), dog ENTPD4 (95% identical), rat Entpd4 (94% identical), mouse Entpd4 (93% identical), mouse Entpd4b (93% identical), guinea pig ENTPD4 (92% identical), pig ENTPD4 (91% identical), tropical clawed frog entpd4 (77% identical), zebrafish entpd4 (70% identical), Caenorhabditis elegans mig-23 (30% identical), and 1 more. Paralogues in human: ENTPD7 (61% identical), ENTPD3 (22% identical), ENTPD2 (21% identical), ENTPD6 (21% identical), ENTPD1 (21% identical), ENTPD5 (19% identical), ENTPD8 (19% identical).
Diseases named in the same sentence as ENTPD4 in open-access papers:
ENTPD4 is named in the same sentence as 8 diseases in open-access papers, as found by Europe PMC text mining. Sharing a sentence is not in itself a finding about the gene and the disease. The quoted sentences say what the papers report.
gastric cancer (3 papers, 2023 to 2025). A primary or metastatic malignant neoplasm involving the stomach. "ENTPD4 encodes an endonuclease that has recently been reported to be active in gastric cancer." (PMID 38773214, 2024). "ENTPD4 participates in promoting gastric cancer development and prostate cancer progression." (PMID 37935721, 2023).
AIDS (1 paper, 2015). A syndrome resulting from the acquired deficiency of cellular immunity caused by the human immunodeficiency virus (HIV). "Our results suggest that down-regulation of ENTPD4 is associated with a slower progression to AIDS." (PMID 26367535, 2015). "Notably, ENTPD4 belongs to the same family as CD39, whose expression has already been associated with AIDS progression; while DNAJB12 is part of the HSP90 pathway, which is involved in the control of HIV latency." (PMID 26367535, 2015).
oral cancer (1 paper, 2024). "The presence of uracil and/or expression patterns of intermediate molecules in purine and pyrimidine pathways, such asCD39, CD73, and P2Y6 receptors together with ENTPD4 and ENTPD5, hold promise as biomarker(s) for oral cancer diagnosis and prognosis." (PMID 38773214, 2024).
tumor (3 papers, 2017 to 2024). "IHC also revealed expression of the UDP-specific ENTPD4, with intense staining of the protein in a high percentage of immune cells in contrast to faint-to-moderate staining in tumor cells." (PMID 38773214, 2024). "The overexpression of CD39, CD73, P2Y6 receptor, and ENTPD4 proteins identified in tumor cells by IHC, was consistent with the over expression of their corresponding genes." (PMID 38773214, 2024). "The current study showed that ENTPD4 was over expressed in GB-OSCC tumor cells." (PMID 38773214, 2024). "Correspondingly, the differential expression of ENTPD4 and ENTPD5 in immune and tumor cells, respectively, indicatedtheir involvement in disease progression." (PMID 38773214, 2024). "Although ENTPD4 was upregulated in immune cells, its expression in tumor cells appeared to be consistent, irrespective of the lymph node status." (PMID 38773214, 2024). "The genomic data showed higher expression of ENTPD4 in tumor samples than in normal samples.On the other hand, ENTPD5 was not prominently expressed by immune cells, but was expressed at high levels in tumor cells." (PMID 38773214, 2024). "The ENTPD4 staining pattern was similar to that of the P2Y6 receptor, with intense staining of immune cells as opposed to tumor cells, which exhibited cytoplasmic staining when in close proximity with immune cells." (PMID 38773214, 2024).
ENTPD4 also shares sentences with these, for which no sentence is quoted: bladder-cancer (1 paper); cancer (1); prostate carcinoma (1); psychiatric disorder (1).